AR (androgen receptor)
Diseases named in the same sentence as AR in open-access papers (continued):
Sharing a sentence is not in itself a finding about the gene and the disease.
prostate carcinoma (continued). "In prostate cancer cell lines, androgen signaling has been reported to induce recruitment of the AR-topoisomerase II beta (TOP2B) complex, which catalyzes DSBs at regulatory regions of AR target genes." (PMID 24244503, 2013). "Since AR expression levels are low in hormone naive tumors, addition of an inhibitor of PI3K/mTOR to the standard ADT of advanced prostate cancer may therefore be beneficial to patients with PTEN deleted tumor." (PMID 24062990, 2013). "Pretreatment of LNCaP cells with SB-202190 could inhibit androgen receptor mediated activation of the PSA promotor by IL-6, a factor which is known to promote prostate cancer growth." (PMID 23840550, 2013). "In this study we report that AR-positive prostate cancer cell-lines express 50% higher levels of enzymes in the hexosamine biosynthesis pathway (HBP) than AR-negative prostate cell-lines." (PMID 23724116, 2013). "To gain a better understanding of the mechanisms through which BET inhibitors regulate cell growth and death in prostate cancer cell lines, we analyzed basal expression of BET proteins and several oncogenes that are known drivers in prostate cancer, including ERG, MYC, and AR." (PMID 24293458, 2013). "In conclusion, our observations indicated targeting AR, PI3K/Akt, Bcl-2, Src, and EGFR signaling pathway may be a choice for treatment of castration-resistant AR-positive prostate cancers." (PMID 24349321, 2013). "Given its robust modulation of several cellular pathways that are highly relevant to prostate cancer such as AR signaling and the cyclin D1/CDK4/RB axis, we tested whether SMIP004 exhibited anti-prostate cancer activity in murine xenograft models." (PMID 23902736, 2013). "Although the role of AR in survival and proliferation of prostate cancer cells is usually attributed to its role as a transcription factor, there is increasing evidence for a non-transcriptional role of AR in a variety of cellular processes." (PMID 23363843, 2013). "Oral administration of triol at 20 mg/kg for three weeks reduced the average tumor volume of AR-negative androgen-insensitive PC-3 prostate cancer cells by 65%." (PMID 23785446, 2013). "The importance of Sp1 binding suggests that therapy targeting the AR-Sp1 complex may dampen VEGF induced angiogenesis and, thereby, block prostate cancer progression, helping to maintain the indolent form of prostate cancer." (PMID 23369005, 2013). "Several of these compounds inhibited the activity of both mutant and wild-type forms of the androgen receptor, and suppressed the growth of both enzalutamide-resistant and nonresistant prostate cancer cells." (PMID 23580326, 2013). "By searching for pairs sense–antisense situated in androgen-regulated tag clusters that possess AR (androgen receptor)-binding sites, the authors identified CTBP1-AS as an androgen-responsive lncRNA, whose expression is generally up-regulated in prostate cancer." (PMID 23875687, 2013). "In summary, we have established a new AR-negative prostate cancer cell line that is derived from PC3 cells and that recapitulates the osteoblastic phenotype of prostate cancer in bone." (PMID 24069383, 2013). "A similar study also demonstrated that high levels of AR inhibited the production of MUC1 and AR-negative prostatic cancer cells expressed high level of MUC1." (PMID 23451223, 2013). "This study demonstrates that functional AR variant signaling does not confer resistance to HSP90 inhibition, yields insight into the interaction between AR and HSP90 and provides further impetus for the clinical application of HSP90 inhibitors in advanced prostate cancer." (PMID 23674566, 2013). "These pathways permit the AR to be activated, amplified, enhanced or bypassed without androgen stimulation, thus leading to the development of prostate cancer." (PMID 24082997, 2013).
prostate carcinoma (continued). "For example, in prostate cancer LNCaP cells, forkhead transcription factor (FOXO3a) that is the phosphatidylinositol 3-kinase (PI3K/Akt) downstream substrate, is a positive regulator for the induction of androgen receptor (AR) gene expression." (PMID 23445528, 2013). "Six drugs have been launched for the treatment of castration-resistant prostate cancer since 2010, i.e., CYP17 inhibitor Abiraterone, AR antagonist Enzalutamide, cytotoxic agent Cabazitaxel, vaccine Sipuleucel-T, RANKL antibody Denosumab and radiopharmaceutical Alpharadin." (PMID 23880851, 2013). "AR regulates expression of PSA and is a key regulator of prostate cancer growth." (PMID 24062781, 2013). "Together, our data provides rationale for the clinical translation of PAN combined with BEZ235 for treatment of advanced prostate cancer, independent of AR status." (PMID 24163230, 2013). "In theory, these AR variants lacking LBD function as constitutively active in a ligand-independent manner, and prostate cancer cells expressing the AR variants are resistant to ADT including CYP17A inhibitors." (PMID 23896594, 2013). "Irrespective of the exact mechanism, SMIP004-induced AR downregulation is significant for advanced prostate cancer, which typically maintains dependence on the AR protein even after progression to castration resistance." (PMID 23902736, 2013). "In addition, experiments carried out in prostate cancer cell lines revealed that androgen treatment up-regulates GNMT expression and that the AR directly binds to the GNMT promoter." (PMID 23997240, 2013). "Because PI3K/Akt and ERK pathways can regulate prostate cancer survival through the AR pathway, we investigated whether inhibiting PI3K/Akt and ERK pathways by kinase-specific inhibitors could affect AR phosphorylation." (PMID 23566222, 2013). "We show that mahanine induces the degradation of DNMT1 and DNMT3B via the ubiquitin-proteasome mediated pathway in both androgen-responsive LNCaP and androgen receptor-negative PC3 human prostate cancer cells." (PMID 24001151, 2013). "For instance, AR gene amplification is frequently observed in prostate cancer but not in breast cancer, despite receptor overexpression." (PMID 24324894, 2013). "Id4 also restores androgen receptor expression and activity in the androgen receptor negative prostate cancer cell line DU145." (PMID 23786676, 2013). "Collectively, PI3K/AKT/mTOR pathway seems to contribute prostate cancer progression not through activation of AR but by facilitating survival of prostate cancer cells upon androgen deprivation." (PMID 23896594, 2013). "In addition to the AR target genes, prostate-specific antigen (PSA) is an important biological marker for the clinical diagnosis of human prostate cancer." (PMID 22666381, 2012). "Thus, to further explore the mechanism of MAP3K11 regulation of prostate cancer cell growth and AR transcription, we tested if MAP3K11 knockdown regulated AR Ser 650 phosphorylation since MAP3K11 is an upstream regulator of JNK activity." (PMID 22761715, 2012). "AR-negative PC3 human prostate cancer cells served as a negative control of antiandrogen sensitivity." (PMID 22509301, 2012). "Nevertheless, unlike the human form, canine prostate cancer is an uncommon neoplasm which does not appear to respond to androgen deprivation, and most canine prostate cancers do not express the androgen receptor." (PMID 22784304, 2012). "Atorvastatin induces autophagy in the androgen receptor negative prostate cancer PC-3 cells through the activation of LC3 transcription." (PMID 22363680, 2012). "Combined, the data suggest that the protein expression levels of AR and PSMA may correlate to the progression and metastatic sites of prostate cancer." (PMID 23041906, 2012).
prostate carcinoma (continued). "On the other hand, RWJ-241947 increased E-cadherin and lowered protein expression of prostate-specific antigen without downregulating the androgen receptor in androgen-dependent LNCaP prostate cancer cells." (PMID 23213321, 2012). "HOXB13, silenced in androgen receptor-negative (AR−) prostate cancer cells, plays a role in AR− prostate cancer cell growth arrest." (PMID 22808286, 2012). "A recent study suggests that PELP1 mediates androgen receptor activation in the absence of androgens in PCa cells and that disruption of the complex between androgen receptor and PELP1 may be a viable therapeutic strategy in advanced prostate cancer." (PMID 22812534, 2012). "Nonetheless, crosstalk between the AR and EGFR pathways remains unclear in bladder cancer, although it has been widely studied in prostate cancer." (PMID 22922989, 2012). "COUP-TF I also strongly inhibited AR transactivation, but it was expressed neither in mouse prostate (data not shown) nor in prostate cancer cell lines." (PMID 23145053, 2012). "Surprisingly, although ERG1C1 expression was associated with AR and AR driven ERG expression in clinical prostate cancers, no major changes were observed in the expression of ERGIC1 mRNA expression in response to AR silencing." (PMID 22761906, 2012). "Although the majority of human prostate-cancer cell lines are reported to be AR-negative, several studies have indicated that the DU-145 and PC-3 prostate-cancer cell lines express detectable levels of the AR mRNA." (PMID 23130941, 2012). "Cell culture experiments of LNCaP prostate cancer cells co-treated with dihydrotestosterone (DHT) and ARE-targeted polyamides have shown decreased expression of several AR-driven genes such as PSA, KLK2, and TMPRSS2 when compared to samples treated with DHT alone." (PMID 22907527, 2012). "On the other hand thus far, no inherited variations in AR, estrogen receptor-1 (ESR1), or estrogen receptor-2 (ESR2) genes have been found associated with prostate cancer aggressiveness or with the efficacy of androgen deprivation in Caucasian populations." (PMID 22956944, 2012). "The androgen-independent prostate cancer cell line DU145 lacks endogenous PLZF expression and that expression could be restored by the ectopic expression of the androgen receptor (AR)." (PMID 22822476, 2012). "Intracellular levels of AR, PSA and GSK-3β in different prostate cancer cell lines." (PMID 21980429, 2011). "Additionally, Src-induced tyrosine phosphorylation of AR, especially AR Y534, was critical for AR activation, and Src-ARY534 phosphorylation was important for cell proliferation under androgen-depleted conditions in prostate cancer cells." (PMID 22110995, 2011). "Aberrant hyper-methylation of the AR promoter has been detected in the AR negative metastatic prostate cancer cell lines DU-145 and TSU-PR1." (PMID 21966451, 2011). "Moreover, a number of potent second-generation AR inhibitors such as abiraterone and MDV3100 are currently being studied in androgen-refractory prostate cancer." (PMID 21457548, 2011). "Together, these results infer a potential role for epigenetic therapies such as 5-aza-CdR in the treatment of prostate cancer regardless of AR or androgen status." (PMID 21980513, 2011). "PC-3 is a commonly used AR-negative human prostate cancer cell line established from a bone-derived metastasis." (PMID 21859492, 2011). "Since the discovery, in the 1940s, that prostate cancer is dependent on the male sex hormones, initially castration and subsequently various forms of ADT, either alone or combined with androgen receptor (AR) antagonists, have been the main therapy for metastatic disease." (PMID 21980513, 2011). "However, compelling data, including RNAi knockdown and the introduction of antagonists of the androgen receptor (AR), indicate that AR is still necessary for ADI prostate cancer growth." (PMID 21267413, 2011).
prostate carcinoma (continued). "In prostate cancer cells, these effects would be anticipated to counteract the anti-proliferative effects of 1,25(OH)2D3, suggesting that not all interactions between AR- and VDR-mediated signaling are beneficial." (PMID 21592394, 2011). "Three identified NLS were not functional in AR-positive prostate cancer (LNCaP and 22RV1) cells, which led to localization of p44/WDR77 in cytoplasm." (PMID 21789256, 2011). "Human Du145 and PC3 prostate cancer cells are frequently used as AR negative control cells, but we detected some expression of AR in these cell lines as well." (PMID 21935435, 2011). "In this study, we also provide evidence that 5-aza-CdR does not require expression of a functional AR to elicit its effects in prostate cancer cells." (PMID 21980513, 2011). "In addition, transient expression of PTEN with wild-type AR suppresses AR activity on androgen-activated MMTV or GRE driven reporters in DU145 and PC-3 prostate cancer cell lines." (PMID 21487159, 2011). "Furthermore, to our knowledge, this is the first publication of evidence that SRD5A3 has at least one nARE and that AR directly binds to this nARE region, demonstrating that SRD5A3 is under transcription inhibition by AR in prostate cancer cells." (PMID 22194926, 2011). "We further found that p44/WDR77 NLS signals are not functional in AR-positive prostate cancer cells, resulting in accumulation of p44/WDR77 in the cytoplasm of such cells." (PMID 21789256, 2011). "Activated TPL2 kinase itself or its downstream kinases may phosphorylate AR, which induces the dimerization and nuclear translocation of AR, and ultimately activates its target gene expressions for ADI prostate cancer cell growth." (PMID 21267413, 2011). "In prostate cancer, SFN treatment inhibited HDAC6, resulting in hyperacetylation of HSP90, disruption of the HSP90-androgen receptor (AR) interaction, and consequently, proteolytic degradation of AR." (PMID 20976254, 2010). "One potential criticism of AR-driven transgenic models of prostate cancer is that the system does not reflect the human disease." (PMID 20195545, 2010). "One potentially important mechanism is the maintenance of androgen receptor (AR) signalling in hormone-refractory prostate cancer by crosstalk between AR and nonsteroidal molecules, including cytokines and growth factors." (PMID 19844233, 2009). "In this study, we evaluated R-568-induced effect on cellular survival in two prostate cancer cell lines, androgen receptor-positive LNCaP cells and androgen receptor-negative PC-3 cells." (PMID 19602280, 2009). "Using two commonly used prostate cancer cell lines, AR-positive LNCaP and AR-negative PC-3, we demonstrated that R-568 reduced cell viability of both cell lines in a dose- and time-dependent manner." (PMID 19602280, 2009). "Unlike prostate cancer, where AR is sustaining growth of cancer cells, androgen signaling in breast cancer represents a restraint to cancer cell growth, and it has been shown that AR expression correlates with a better prognosis." (PMID 19695104, 2009). "As a first step elucidating the molecular mechanisms of the chemopreventive effects of RSV on prostate cancer development, experiments were designed to clarify whether RSV regulates AR target gene expression by repressing AR transcriptional activity." (PMID 19816598, 2009). "However, over-expression of both AR and AKT is sufficient to induce prostate carcinomas with progression to androgen-independent disease 77, implying that the initiating cell does not need to be a stem cell, at least in this mouse model." (PMID 19040209, 2009). "Concentrations of 50–60 nM would still be necessary for these two ligands to activate AR, and these levels are clearly supraphysiologic and not likely achievable in normal individuals, or in patients with prostate cancer receiving hormonal manipulation." (PMID 18978937, 2008).
prostate carcinoma (continued). "As no previous studies have investigated in vivo the combination of a microtubule disruptor and 2DG in breast and prostate cancer, the efficacy of STX140 and 2DG was assessed in the MCF-7 (ER-positive, breast) and LNCaP (AR-positive, prostate) xenograft models." (PMID 18985042, 2008). "This response is similar to cell cycle effects of AR when is re-introduced to the PC3 prostate cancer cell line; OHF did not have any appreciable effect on the cell cycle." (PMID 18978937, 2008). "Furthermore, we have not been able to significantly translate any mechanistic advances since AR cloning into improving the fate of patients affected by AIS and ADI prostate cancer." (PMID 18978937, 2008). "LNCaP, a high AR-expressing androgen responsive prostate cancer cell line, and PC3, a low AR-expressing androgen-independent prostate cancer cell line, were respectively used as positive and negative controls for DHT-stimulated cell proliferation." (PMID 18433501, 2008). "This study adds to the list of publications suggesting that nuclear AR expression in tumor tissue is non-informative as a prognostic marker in prostate cancer." (PMID 19025630, 2008). "Indeed, several recent studies suggest that AR continues to play a key role in the survival and proliferation of HID prostate cancers via HER2 signalisation, explaining the role of trastuzumab in the combination with docetaxel." (PMID 17211467, 2007). "For example, expression of the androgen receptor (AR) does not appear to correlate with response to hormone therapy in prostate cancer, and AR protein is expressed fairly homogeneously in primary tumors, recurrent local tumors, and metastases." (PMID 17598908, 2007). "In PC-3, an androgen-insensitive prostate cancer cell line not expressing AR but having ERα, RES treatment also produced a concentration-dependent reduction in ERα with a maximum effect at 100–150 μM." (PMID 17486135, 2007). "In tumors with specific AR mutations, BPA promotes therapeutic bypass, suggesting significant negative impact to the clinical management of prostate cancer." (PMID 18007998, 2007). "There are also mechanisms for AR activation in recurrent or advanced prostate cancers in which overexpression is not obligatory." (PMID 17384772, 2007). "Consistent with the negative feedback model, full-length cyclin D1 markedly inhibited cell cycle progression in AR dependent (but not AR negative) prostate cancer cells." (PMID 16863592, 2006). "In another prostate cancer cell line that lacked AR expression restoration of that expression restored AR-dependent cell growth." (PMID 16774685, 2006). "For example, Akt-3 is not expressed in androgen receptor positive prostate cell lines and no constitutive activation of Akt-2 has been observed in prostate cancer cell lines while Akt-1 is constitutively activated in most prostate cancer cell lines." (PMID 16721361, 2006). "Importantly, CD164 is expressed in human prostate cancer tissues paralleling the PSA expression, and negatively correlating with AR expression." (PMID 16859559, 2006). "By bypassing the AR completely, prostate cancer cells survive independent of ligand-mediated or nonligand-mediated AR activation." (PMID 16983403, 2006). "Two major pathways are shown to be activated in organ-confined, non-metastatic prostate cancer: those regulated by the androgen receptor and by receptor tyrosine kinases." (PMID 16107210, 2005). "The biological interpretation of the results lead us to propose that two major pathways are predominantly activated in organ-confined, non-metastatic prostate cancer: those regulated by androgen receptor and by receptor tyrosine kinases." (PMID 16107210, 2005). "Therefore, we examined AR transactivation of MMTV-luc in two androgen-independent prostate cancer cell lines, PC3 and DU145, that had been transfected with wild-type AR." (PMID 15583694, 2005).